KRT5 (keratin 5)
Diseases named in the same sentence as KRT5 in open-access papers (continued):
Sharing a sentence is not in itself a finding about the gene and the disease.
tumor (continued). "The use of the two different promoters led to different tumor types: the gfap promoter drove expression in CNS with 50% incidence of tumor development; the krt5 promoter induced aggressive nerve sheath tumors, supporting the idea that the origin of the tumor initiating cells affect tumor cell types." (PMID 28930163, 2017). "Furthermore, most of the tumor cells expressed the lung regeneration markers p63, keratin 5/14, and Lgr 5/6." (PMID 25659078, 2015). "These tumours also expressed cytokeratin 5/6 and cytokeratin 14 (another basal cytokeratin) on IHC." (PMID 25887320, 2015). "For A1708E, previously shown to be functionally compromised, analysis of oestrogen receptor, cytokeratin 5/6, and cytokeratin 14 tumour expression data significantly strengthened the prediction of pathogenicity, giving a posterior probability of pathogenicity of 99%." (PMID 18036263, 2007). "Moreover, by analyzing FGFR1 mRNA expression, a stromal-rich tumor subtype has been identified that lacks both KRT5 and KRT20 mRNA expression and is almost resistant to upfront chemotherapy (0% pCR rate in FGFR1 high tumors vs. 66.7% pCR rate in FGFR1 low tumors)." (PMID 35887247, 2022). "Therefore, we used a stemness gene associated with tumor cell heterogeneity and SOX2, SOX4, SOX9, basal cell markers KRT5, KRT14, immune genes PD-Ll and epithelial-mesenchymal transition E-cadherin to study heterogeneous cell and malignant transformation mechanisms." (PMID 36056339, 2022). "In addition, they may also have scattered positive KRT5/6 cells, and this positivity was present in less than 10% of the tumor cells." (PMID 32546765, 2020). "Tumor‐derived cells were morphologically indistinguishable from normal human airway epithelial cells in 3T3 + Y culture and expressed proteins associated with airway basal cells, such as keratin 5 and the transcription factor p63." (PMID 29569246, 2018). "The presence of OvCa+/CD45- CTCs at baseline was associated with significantly lower levels of KRT5 (mean lg2 transformed gene expression 1.12 vs. 0.10, p = 0.040) and KRT7 (mean lg2 transformed gene expression 1.34 vs. 0.36, p = 0.034) gene expression in the corresponding tumor tissue samples." (PMID 29290959, 2017). "As indicated by immunostaining for the myoepithelial protein keratin 5, the proportion of myoepithelial cells in Py230 outgrowths is low, indicating a bias towards development of luminal tumor cells, consistent with multiple studies indicating that PyVmT oncogenic pathways form luminal tumors." (PMID 26467658, 2015). "In addition, associations between NUCKS1 and other tumor subtype markers, including estrogen receptor (ER), progesterone receptor (PR), human epidermal growth factor receptor 2 (HER2), Ki-67 and cytokeratin 5/6 (CK 5/6), were investigated." (PMID 25187794, 2014). "We also observed the enrichment of CDKN2A (p16), SERPINB3, KRT5, and TP63, which are well‐established biomarkers for HPV‐positive neoplasia and are typically expressed in tumour areas." (PMID 41362277, 2026). "Conversely, myoepithelial tumor cells expressed p63 and smooth muscle actin (SMA), while basal cells typically exhibited expression of cytokeratin 5/6 (CK5/6) and p63." (PMID 41536110, 2026). "Proteomic analysis of serum samples from PDAC patients with well‐characterized tumor subtypes revealed that several keratins, including KRT2, KRT5, KRT10, and KRT77, were highly abundant in samples from patients with basal‐like tumors." (PMID 39478658, 2025). "The tumor subtypes reflected by the patient-derived ex vivo cultures were validated by qPCR analysis of keratinization (CNFN, CRNN), basal (KRT5, KRT6), and luminal markers (KRT7, GATA3)." (PMID 41387887, 2025). "Taken together, these findings suggest that anti-PD-L1-CRT therapy dramatically alters expression of cytoskeletal genes, such as KRT5 and CDH1, in tumours, along with changes in cell morphology." (PMID 40670667, 2025).
tumor (continued). "Differential gene expression analysis demonstrated that Tum_1 tumor cells predominantly expressed basal cell marker genes such as KRT14, KRT5, and KRT15, and exhibited high levels of genes related to cell adhesion, including ITGB4 and ITGA6." (PMID 40470730, 2025). "The peaks of epithelial cells and tumor cells were notably enriched in the gene sets of ‘VIM, KRT5, KRT17’ and ‘KRT8, KRT18, FOXA1’, respectively." (PMID 38581422, 2024). "Luminal tumours were identified as KRT20+/GATA3+/FOXA1+ and basal tumours as KRT5/6+/KRT14+/GATA3−/FOXA1−." (PMID 39594166, 2024). "In the present case, IHC examination of the tumor revealed that vimentin was positively stained, P63, KRT14, S-100 was focally positive, Ki-67(80%), while KRT5/6, KRT7, GFAP, calponin, SMA, KRT-PAN, SOX10, mammaglobin was negative." (PMID 37705036, 2023). "Furthermore, it is most likely that TRIM29 could regulate expression of ZNF750 and KRT5 in other tumors, as TRIM29 expression positively correlated with the expression of ZNF750 and KRT5 significantly in 18 tumor types, such as BLCA, CESC, HNSC, LUSC, PRAD, and SKCM." (PMID 37365152, 2023). "We next compared tumours from the SCC and ADC subtypes, as determined by keratin 5 (Krt5), thyroid transcription factor 1 (Ttf-1/Nkx2-1) and Usp28 staining, in KPL mice." (PMID 37202505, 2023). "Cytokeratin 5 (CK5) and transketolase (TKT) were identified in benign mixed tumor cells and complex carcinoma cells." (PMID 37893211, 2023). "This presents a convenient test case for SpatialCorr and we indeed identified strong correlation between expected type 1 and type 2 pairs such as KRT1 and KRT10, as well as KRT5 and KRT14, throughout the epidermis and much of the tumor." (PMID 36590683, 2022). "In transgenic mice overexpressing GLI2 driven by the keratin 5 (K5) promoter, CCND1 and CCND2 were significantly upregulated in BCC biopsies, promoting sustained tumor growth and expansion of BCC." (PMID 34572373, 2021). "Compared to controls, tumor displaying lower SNAI1, PECAM1 and VIM and higher TP63, KRT14, KRT5 and PTPRC (CD45) RNAs (PyMT-VE-CadhSnail1KO tumor signature) presented a longer overall survival, strengthen our mice results." (PMID 34335957, 2021). "The H&E staining and 11 IHC markers (Ki67, P63, GATA3, KRT5/6, KRT20, E-cadherin, 34βE12, PD-L1, EGFR, Nectin4, and HER2) were used to evaluate tumor phenotype maintenance." (PMID 35432811, 2021). "Formalin-fixed paraffin-embedded tumour tissue samples from TUR-BT of 54 patients (42 males, 12 females, median age of 64) with MIBC were analyzed for KRT20, KRT5, ESR1, and ERBB2 mRNA expression." (PMID 34073233, 2021). "Tumours were considered as luminal type if they had a high expression of ERBB2, ESR1, or KRT20 while showing a low expression of KRT5." (PMID 34073233, 2021). "One tumour (ID-87) with P63 expression also showed very high levels of EGFR and KRT5, highly suggestive of squamous cell differentiation." (PMID 31537838, 2019). "Immunohistochemical studies confirmed the tumor cells to be immunoreactive with cytokeratin AE1/3, cytokeratin 5/6, cytokeratin 7, p63, and SOX10." (PMID 29651355, 2018). "Here, we show that human spSCC tumours also feature strong nuclear localisation of YAP and overexpression of activated YAP (NLS-YAP-5SA) with Keratin-5 (K5-CreERt) is sufficient to induce rapid formation of both SCC and spSCC in mice." (PMID 30231971, 2018). "There was the expected corresponding decrease in basal cell markers (KRT5 and TP63) and increase in expression of luminal cytokeratin markers in tumor cells (KRT8 and KRT18)." (PMID 27935821, 2017). "The basal/SCC‐like cases in the same consensus cluster showed almost no expression of FGFR3 and CCND1, whereas the reverse was seen for KRT5 and CDH3 tumour‐cell expression." (PMID 28195647, 2017).
tumor (continued). "The muscle invasive tumour, however, showed a basal subtype (higher expression of CDH3, CD44, KRT5 and KRT6A) and likewise high aggressiveness (higher expression of KPNA2, BIRC5, CDC25B, COL4A1, and MSN)." (PMID 28916750, 2017). "Genes that were downregulated and hypermethylated in ADCs were squamous markers such as DSC3 and KRT5, as well as transcription factors such as FOXE1 and TP73, whose isoforms have demonstrated both tumor suppressor and oncogenic properties." (PMID 28787442, 2017). "Consistently, GATA6 was significantly lower in BAS-L tumours (p<0.001), and GATA6-silenced PaTu8988S cells ectopically expressed the basal keratins KRT5 and KRT14." (PMID 27325420, 2017). "Additional staining for cytokeratin 5/6 (KRT5/6), epidermal growth factor receptor (EGFR) and Ki-67 has also been used as a surrogate for gene expression profiling to allocate tumours to luminal A, luminal B, HER2 or basal-like molecular subtypes." (PMID 25633981, 2015). "Immunohistochemically, the tumor was positive for pancytokeratin, high-molecular-weight keratin, CEA, cytokeratin 5/6, and p63." (PMID 24639909, 2014). "Regarding the expression of luminal and basal biomarkers, Layer3.1 tumor presented higher expression of KRT20, a luminal-papillary biomarker, whereas Layer3.2 had higher expression of KRT5, KRT6a, KRT14, and CD44 basal biomarkers, but also PGM5, DES, and SGCD luminal-infiltrated biomarkers." (PMID 41516353, 2026). "Original tumor tissue of p-UC was characterized immunohistochemically for luminal urothelial differentiation by negative KRT5/6 staining (Fig. 3Aii) and strong GATA3 staining (Fig. 3Aiii)." (PMID 40251219, 2025). "Single-cell expression analysis revealed that KRT5 and FABP7 were highly enriched in tumor cells, UGT2B4 was predominantly expressed in epithelial cells, BIRC3 and KLRB1 were enriched in CD8+ T cells, while MRC1 and CD209 were highly expressed in monocytes/macrophages." (PMID 40612672, 2025). "The association of the AR status with clinicopathological factors (age, stage, tumor diameter, lymph node invasion, metastatic spread, Ki-67 score, EGFR score, and cytokeratin 5/6 score) and the disease outcome (disease-free survival—DFS—and overall survival—OS) was investigated." (PMID 40150035, 2025). "While TKO tumor cells were primarily NE (ASCL1+), TKO-Nicd1 organoid tumor cells were non-NE and expressed markers of prostate epithelium (Krt5+, Krt8+, Hes1+)." (PMID 39024561, 2024). "Luminal tumours were (GATA3, FOXA1+), and basal/squamous tumours were (KRT5/6, KRT14+)." (PMID 39594166, 2024). "Through assay for transposase-accessible chromatin using sequencing (ATAC-seq), we detected increased chromatin openness of squamous markers (TP63, KRT5, KRT6A and KRT14) and reduced chromatin accessibility of adenomatous markers (KRT7 and MLPH) in the DR tumor cells." (PMID 39687207, 2024). "Assessment of epithelial marker genes showed similar expression scores across fresh and FFPE tissue samples, as EPCAM, KRT5, SCGB3A2, FOXJ1, AGER and SFTPC marked tumor epithelial, Basal, Transitional, Ciliated, AT1, and AT2 cells, respectively, across the datasets." (PMID 38300468, 2024). "Immunohistochemistry revealed partially preserved cytokeratins, especially cytokeratin 5, with carcinoma cells being vimentin negative and tumor stroma vimentin positive." (PMID 39463382, 2024). "Comparing the bulk transcriptome profiles of the TD and nonTD patients, the TD patients exhibited upregulation of keratins (KRT81, KRT6B, KRT15, KRT5) and kallikreins (KLK5, KLK6, KLK7), indicating active extracellular matrix (ECM) remodeling and tumor expansion." (PMID 39664386, 2024).
tumor (continued). "Interestingly, contrary to the transcriptomic findings, KRT5 and KRT19 were coexpressed in most tumour cells and normal basal epithelial cells in IMC images, except for a subset of KRT5–/KRT19+ tumour cells in P04." (PMID 37349991, 2023). "Additionally, silencing of BCL11A reduced the levels of SCC markers (KRT5 and TP63) and inhibited tumor growth." (PMID 37372998, 2023). "Therefore, our study revealed that low expression of FLNA, DPYSL3, KRT5, and TNC promotes tumor migration and development during the pathogenesis of PCa." (PMID 37251946, 2023). "Similar to the patients’ SARC tumor component and in contrast to the UroCa component, organoids were negative for additional epithelial markers (KRT5, KRT8), yet showed a strong expression of Vimentin, hallmark of mesenchymal-like cells." (PMID 37919480, 2023). "To investigate whether one lineage is important for metastasis than the other, we analyzed lungs from Krt5-CreERT/Rosa26-mTmG/MMTV-PyMT and Krt8-CreERT/Rosa26-mTmG/MMTV-PyMT tumor bearing mice." (PMID 36859337, 2023). "Cytokeratin profiling of control and Kmt2c null tumours showed lack of Keratin 5 (Krt5) and maintenance of Keratin 8 abundance (Krt8)." (PMID 36933062, 2023). "Different tumor-initiating cells affect the tumor type; in fact, overexpression of KRASG12V under the control of the krt5 gene promoter induced low frequency brain tumors in the ventricular zones (VZ) that resemble malignant peripheral nerve sheath tumors (MPNSTs)." (PMID 35706426, 2022). "Therefore, the cancer cells mainly expressed the known CSCC‐associated gene SERPINB3 (serpin family B member 3), tumor genes TP63, CDKN2A, and keratin gene KRT5 in squamous cells." (PMID 35986392, 2022). "Using unsupervised hierarchical clustering of six subtyping genes assessed by multiplex RNA hybridization (basal differentiation: KRT5, KRT14, CD44; luminal differentiation: KRT20, GATA3, and FOXA1), 28 tumor samples were each classified as either basal or luminal subtypes." (PMID 36142180, 2022). "At the same time, immunohistochemistry in tumor 2 showed that these malignant cells were positive for ER and GATA binding protein 3 (GATA-3) but negative for epidermal growth factor receptor (EGFR) and cytokeratin 5/6 (CK5/6)." (PMID 36578949, 2022). "Besides the differential expression of KRT5 and KRT19 between the margin and tumor center, KRT6B, KRT8, KRT10, and KRT17 were identified among the proteins differentiating the cancer from control tissue." (PMID 35512017, 2022). "Tumor grade was significantly negatively correlated with the expression of KRT5 (rs = −0.225; p = 0.029) and showed a trend for a negative correlation with AR (rs = −0.201; p = 0.053)." (PMID 34209360, 2021). "Also, in the model P8X26, the expression of 8 markers (i.e., Ki67, P63, GATA3, KRT5/6, KRT20, 34βE12, EGFR, and HER2) was similar between the original tumor and different generations." (PMID 35432811, 2021). "The tumor cells expressed synaptophysin, cytokeratin MNF 116,cytokeratin 5/6 (CK5/6), cell adhesion molecule 5.2 (CAM5.2), p40, p63, without expression of thyroidtranscription factor 1 (TTF-1), GATA binding protein 3 (GATA3), chromogranin A, CD56, CD45, orS100." (PMID 34106022, 2021). "Furthermore, the gene expression alterations in tumour tissues were consistent with the in vitro observations: upregulation of PTGS2 and CYP2E1 and down-regulation of TP63 and KRT5." (PMID 33359448, 2021). "However, if a tumor cannot be diagnosed based only on histological features, staining with positive markers, including CK17 (cytokeratin 17), CK15 (cytokeratin 15), CK5/6 (cytokeratin 5/6), and p63, should be supportive." (PMID 34064849, 2021).
tumor (continued). "Interestingly, in the model P8X20, the expression level of 7 markers (i.e., Ki67, KRT5/6, KRT20, 34βE12, PD-L1, EGFR, and Nectin4) was exactly similar between the patient tumor and the next generations." (PMID 35432811, 2021). "Early hyperplastic tumor cells showed high expression of Krt6 and Krt5, decreased expression of Loricrin (Lor), and a lack of Krt7 expression." (PMID 31110179, 2019). "These tumours also on the protein level typically showed no or low expression of KRT5 and KRT14, aberrant expression of KRT20 and a low expression of EGFR, but a high expression of ERBB2." (PMID 30258198, 2018). "Cytokeratin 5 positivity progressively decreased in the primary tumors and was significantly lower at 3 w p.i. in the 4T1 + RAW264.7 compared to the 4T1 tumors, indicative for enhanced tumor cell breakthrough in the presence of additional macrophages." (PMID 30111338, 2018). "Furthermore, we observed a significantly lower level of H3K27me3 mark in Sox2, Ngfr and Krt5/6 loci compared to those in ADC tumours, consistent with de-repression of these squamous loci in SCC tumours." (PMID 28387316, 2017). "In Lkb1-deleted tumours, purely squamous and transitioning tumours with areas of both ADC and SCC histology, as determined by immunohistochemistry (IHC) for the squamous markers KRT5, p63 and SOX2, were present." (PMID 28387316, 2017). "GA inhibited tumor cell proliferation in a concentration- and time- dependent manner while nontumorigenic luminal epithelial cells derived from a normal C57BL/6 prostate (B6WT, KRT8+/ARlow >80%, KRT8+/KRT5+ <20%) were relatively resistant to GA." (PMID 29100379, 2017). "Primary tumours from all lines were negative for progesterone receptor, Erb-b2/Neu and cytokeratin 5/6, but positive for epidermal growth factor receptor (EGFR)." (PMID 25633981, 2015). "The subdivision of tumors into 5 sub-branches shows a non-random distribution of tumor subtypes and immunohistochemical staining of KRT5/6, EGFR and KIT." (PMID 17910759, 2007). "Immunocytochemically, tumor cells from all cases examined did not express keratin 10, while strong positivity to anti-keratin 5, 8, and 18 antibodies, and anti-UEL antibody was observed." (PMID 15357873, 2004). "Altered molecular targets, such as E-cadherin (CDH1), MMP9, Survivin (BIRC5), Cytokeratin 5 (KRT5), VEGFA, IL15, TNF-α (TNF), TRAIL (TNFSF10), and Tenascin-C (TNC), exhibited increased expression in our study, which correlates with their upregulation in tumor samples from individuals with OC." (PMID 40072102, 2025). "We validated that H3K27ac/H3K4me3 activity at the KRT5 and KRT8/18 loci served as an accurate indicator of epithelial identity and that snCUT&RUN can be used to comprehensively analyze a mixture of samples to infer epithelial changes and the accompanying TF motif changes during tumor progression." (PMID 39622638, 2025). "Specifically, the level 3 classifier shows strong correlations among genes like KRT5, S100A7, KRT16, S100P, and LY6D, while the level 6 classifier exhibits similar patterns with GPR17, RGR, and NPPA, highlighting the complex interplay of genes in tumor subtype classification." (PMID 40802546, 2025).